CHMP4BP1 (charged multivesicular body protein 4B pseudogene 1)
Gene: Protein-coding gene on chromosome 14 (55,271,686 to 55,299,503, forward strand). Ensembl gene ENSG00000258469.
Gene Ontology:
Biological process: late endosome to vacuole transport via multivesicular body sorting pathway; nuclear membrane reassembly; autophagosome maturation; late endosome to lysosome transport; midbody abscission; mitotic metaphase chromosome alignment; multivesicular body sorting pathway; plasma membrane repair; regulation of mitotic spindle assembly; ubiquitin-dependent protein catabolic process via the multivesicular body sorting pathway; vacuolar transport; viral budding from plasma membrane; viral budding via host ESCRT complex
Cellular component: cytoplasmic side of plasma membrane; ESCRT III complex; nuclear envelope; amphisome membrane; kinetochore; kinetochore microtubule; lysosomal membrane; midbody; multivesicular body membrane
Homologues: Orthologues: chimpanzee CHMP4BP1 (97% identical), mouse Chmp4b (90% identical), rat Chmp4b (90% identical), dog CHMP4B (89% identical), guinea pig CHMP4B (89% identical), rat Chmp4bl1 (88% identical), tropical clawed frog chmp4b (85% identical), zebrafish chmp4ba (81% identical), zebrafish chmp4bb (79% identical), Caenorhabditis elegans vps-32.1 (61% identical), Drosophila melanogaster shrb (57% identical). Paralogues in human: CHMP4B (91% identical), CHMP4C (63% identical), CHMP4A (62% identical), CHMP5 (29% identical), CHMP7 (23% identical).